BRAF (B-Raf proto-oncogene, serine/threonine kinase)
Diseases named in the same sentence as BRAF in open-access papers (continued):
Sharing a sentence is not in itself a finding about the gene and the disease.
colorectal cancer (continued). "Our study demonstrated the known driver mutations seen in colorectal cancer such as APC, KRAS, BRAF and PIK3CA, but also more novel mutations that would potentially be targetable by molecular agents." (PMID 33632293, 2021). "A total of 146 colorectal cancer samples were sent to Nantes University Hospital between 1 January and 31 December 2019, to test for KRAS, NRAS or BRAF mutations by NGS and microsatellite instability by MSI-PCR." (PMID 34439357, 2021). "We began by analysing CRISPR-Cas9 screens used to identify genes that enhance or suppress sensitivity to a BRAF inhibitor (dabrafenib) in a partially-sensitive BRAF-mutant colorectal cancer cell line (HT-29)." (PMID 33478580, 2021). "KRAS mutations, BRAF mutations and SMAD4 mutations are less frequent in CSM2 colorectal cancers than in other subtypes." (PMID 34577783, 2021). "It should also be noted that the expression pattern of BRAF mutant colorectal cancer is very diverse, and several subtypes have been identified." (PMID 34381786, 2021). "BRAF and RAS mutations are known to be mutually exclusive, but simultaneous mutations have been described in colorectal cancer." (PMID 33716974, 2021). "This comprehensive integrative -omics analysis confirms known and adds novel genes, proteins and metabolic pathways regulated by mutant KRAS and BRAF signaling in colorectal cancer." (PMID 34233735, 2021). "In this study, we analyzed a cohort of six colorectal cancer patients harboring KRAS mutations and with wild-type BRAF from a transcriptional perspective, with the aim of elucidating the role of the stromal cells in tumor progression." (PMID 34439343, 2021). "These assays demonstrate a strong relationship between the presence of the BRAF mutation (V600E) and resistance to anti-EGFR therapy in colorectal cancer." (PMID 34150757, 2021). "One MSI-H:BRAF mutant and two MSI-H:BRAF wild-type colorectal cancers identified by IHC were classified as MSS using CGE." (PMID 34198876, 2021). "Our in vitro study also indicated that AREG significantly enhanced the growth of cetuximab-sensitive RAS/BRAF wild-type colorectal cancer cell lines with increased phosphorylation of AKT and ERK1/2." (PMID 34893673, 2021). "The generation and activation of RAF dimer will lead to the reactivation of MEK-ERK pathway, which is the reason why colorectal cancer is resistant to BRAF inhibitors." (PMID 34976824, 2021). "Right-sided (proximal) colorectal cancer (CRC) has a poor prognosis and a distinct mutational profile, characterized by oncogenic BRAF mutations and aberrations in mismatch repair and TGFβ signalling." (PMID 34103493, 2021). "In POCHER, the study showed that cetuximab combined with FOLFOXIRI administered as conversion chemotherapy can achieve 60% of the R0 resection rate in patients with initially unresectable liver metastases from wild-type RAS/BRAF colorectal cancer." (PMID 34567559, 2021). "It is notable that studies on colorectal cancer demonstrated the feasibility of adding anti-EGFR therapy to BRAF inhibitors in order to prevent feedback activation of EGFR receptor." (PMID 34681592, 2021). "The importance of the BRAF status on prognostication of colorectal cancer remains controversial, though current evidence leans towards poor prognostication." (PMID 34940086, 2021). "To define the capacity of colorectal cancer organoids to mirror the genome heterogeneity of the corresponding patient tumor, we compared the mutational status of three genes (KRAS, NRAS, and BRAF) in 19 PDTOs and corresponding tumor tissues." (PMID 34359661, 2021). "The main reason why BRAFV600E-treated colorectal cancer (CRC) develops drug resistance to selective BRAF inhibitors is that BRAF inhibitors can induce autophagy through the AMPK-ULK1 pathway." (PMID 32033142, 2020).
colorectal cancer (continued). "It is well established that loss of DNA mismatch repair functionality results in a hypermutable phenotype (microsatellite instability, or MSI) and that this is common in BRAF mutant colorectal cancers." (PMID 32384699, 2020). "Previous studies have also shown high concordance for blood and tissue alterations, such as those in the KRAS, NRAS, APC, and BRAF genes, in colorectal cancer." (PMID 32187847, 2020). "While the studies on the genomic landscape of colorectal cancers revealed that NTRK fusions are mutually exclusive with driver mutations like KRAS and BRAF mutations." (PMID 33520689, 2020). "In an examination of 10 colorectal cancers, an increase in EMT and stemness was observed in CPE (+) and BRAF mutation (+) cases." (PMID 32481659, 2020). "Among them, EGFR overexpression is an important mechanism of resistance to BRAF inhibitors in colorectal cancer patients." (PMID 32476297, 2020). "The combination of BRAF ± MEK inhibitors with anti-EGFR monoclonal antibodies has achieved promising responses in this highly aggressive subset of colorectal cancer patients leading to improvement in survival and quality of life outcomes." (PMID 32670606, 2020). "In neoplasms of other organs, especially colorectal cancer, ANXA10 is associated with CpG island methylation and BRAF mutation." (PMID 33177783, 2020). "Further study is necessary to assess the role of CIMP in shaping WNT signaling in the context of BRAF mutant colorectal cancer." (PMID 32384699, 2020). "In some organs, however, first-line treatments using molecular targeted drugs are selected based on genetic testing results using tumor tissue specimens, for example, HER2 testing for gastric cancer and RAS/BRAF testing for colorectal cancer." (PMID 31286289, 2020). "Methods: we performed exome-sequencing on 24 BRAF mutant colorectal cancers and analyzed these data in combination with 175 publicly available BRAF mutant colorectal cancer exomes." (PMID 32384699, 2020). "BRAF inhibitors led to hyperactivation of FAK and subsequent upregulation of the Wnt/β-catenin signaling pathway in BRAF-mutant colorectal cancer cells." (PMID 32514188, 2020). "In the present study, we investigated the in-vitro anti-cancer potential of six diarylpentanoids against a panel of BRAF- and KRAS-mutated colorectal cancer cell lines including T84, SW620, LoVo, HT29, NCI-H508, RKO, and LS411N cells." (PMID 32858795, 2020). "Our study has comprehensively assessed the somatic mutation landscape of WNT signaling regulators in a large series of BRAF mutant colorectal cancers, however several limitations remain." (PMID 32384699, 2020). "Collectively, these data indicate that the activating mutation of BRAF and the truncating mutation of APC represent an aggressive subtype of colorectal cancers that occur at a relatively young age in comparison to BRAF mutant cancers more generally." (PMID 32384699, 2020). "While some driver mutations are targetable, others have shown to confer resistance to standard therapy choices such as KRAS, BRAF, and PIK3CA mutations in colorectal cancer." (PMID 32760731, 2020). "An understanding of this biology paved the way for the encouraging results of a clinical trial for combination BRAF–EGFR–MEK inhibitor therapy for treating BRAFV600E colorectal-cancer patients." (PMID 32033280, 2020). "In a preclinical study, colorectal cancer cell lines harboring BRAF V600E demonstrated decreased response to vemurafenib while they showed inhibited survival under vemurafenib and cetuximab combination treatment in culture." (PMID 32770988, 2020). "We obtained exome sequencing data from 175 BRAF mutant colorectal cancers from four previously published studies and sequenced a further 24 BRAF mutant samples collected locally." (PMID 32384699, 2020). "Molecular testing (RAS, BRAF) is currently a routine part of clinical practice in colorectal cancer." (PMID 33344234, 2020).
colorectal cancer (continued). "While combination BRAF and MEK inhibition is proven to be of benefit in V600 mutated cholangiocarcinoma, additional EGFR inhibition is required in V600 mutated colorectal carcinoma." (PMID 32384640, 2020). "The extrapolation of our data to inform Lynch syndrome testing in colorectal cancer patients is problematic given their use of BRAF V600E as a proxy of MLH1 promoter hypermethylation in tumor-based triage." (PMID 30863719, 2019). "KRAS and BRAF are two major oncogenic drivers of colorectal cancer (CRC) that have been frequently described as mutually exclusive, thus the BRAF V600E mutation is not expected to be present in the cases with KRAS mutation." (PMID 29127628, 2019). "EGFR-activation-mediated BRAF inhibitor resistance was described first in V600E BRAF-mutant colorectal cancer." (PMID 31514305, 2019). "In the Pan-Asia ESMO Consensus guideline for colorectal cancer, FOLFOXIRI plus bevacizumab is recommended as first-line therapy in patients with BRAF V600E mutation." (PMID 30800219, 2019). "For this reason, BRAF inhibition in colorectal cancer indirectly results in EGFR receptor activation and subsequent PI3K–Akt pathway activation." (PMID 30667539, 2019). "Primary colorectal cancers frequently harbor somatic mutation of KRAS (~40%), BRAF (~10–15%) and PIK3CA (~10–20%)." (PMID 31769426, 2019). "KRAS, BRAF and PIK3CA were also presented as screen factors in colorectal cancers using their mutations." (PMID 31263147, 2019). "Proliferation and survival related signaling pathways such as PI3K/AKT/mTOR and RAS/RAF/MEK/ERK play important roles in pathogeneses of solid tumors, and KRAS, BRAF, and PIK3CA (PI3K) mutations are the most common in colorectal cancer." (PMID 31624493, 2019). "For example, high levels of vitamin C can selectively kill KRAS- and BRAF-driven colorectal cancer cells by inducing oxidative stress, suppressing glycolysis and the subsequent energy crisis." (PMID 30688660, 2019). "In colorectal cancer, preclinical studies with BRAF inhibitors have reported adaptive feedback reactivation of MAPK signaling involving EGFR." (PMID 30636931, 2019). "In a study of serrated polyps and colorectal cancers, the CIMP-high cancers were more frequently identified with the BRAFV600E mutation, implying a significant association between DNA methylation and BRAF mutational status." (PMID 31581557, 2019). "DHA, which is the oxidized product of AA, induces cell death in colorectal cancer carrying KRAS and BRAF mutation by deactivating glyceraldehyde 3-phosphate dehydrogenase." (PMID 30903981, 2019). "Taken together, these findings suggest that overactivation of Akt contributes to MEK inhibitor resistance in KRAS and BRAF mutant colorectal cancer." (PMID 31769426, 2019). "Meanwhile, exclusive generation of intracellular free radicals, such as hydrogen peroxide (H2O2) and superoxide (O2−), through the oxidation of antioxidants induces apoptotic cell death in KRAS and BRAF mutant colorectal cancer." (PMID 30903981, 2019). "In colorectal cancer, the concordance of KRAS mutation is 56.10% (92/164), and the concordance of BRAF mutations 46.15% (6/13)." (PMID 31650022, 2019). "We explored the association of clinico-pathological variables related to the mutational status of KRAS, NRAS, BRAF, and PIK3CA, genes that are involved in the main pathways of different solid tumors including colorectal cancer." (PMID 31036005, 2019).
colorectal cancer (continued). "We generated tissue models with BRAF-mutant colorectal cancer (CRC) cells (HROC24 and HROC87) and compared treatment responses to two-dimensional (2D) cultures and xenografts." (PMID 31861874, 2019). "Kinase gene fusions account for less than 1% of mCRC overall but are enriched in patients with high microsatellite instability, RAS/BRAF wild-type colorectal cancer." (PMID 31731495, 2019). "Clinically, the staining in BRAF V600E-mutant positive cases can be weak, moderate, to strong, and the distribution can be uniform, nearly uniform, or heterogeneous in colorectal carcinoma." (PMID 31234388, 2019). "According to statistical analysis of the COSMIC database, colorectal carcinoma cells contain high rates of the gene mutation of KRAS (34%), PIK3CA (14%) and BRAF (10%), the major downstream signaling molecules of EGFR." (PMID 31367332, 2019). "About 20% of BRAF-mutant colorectal cancers display MMR/MSI-H, due to MLH1 gene epigenetic silencing." (PMID 29652830, 2018). "Baseline and clinical characteristics of colorectal cancer cases by KRAS and BRAF mutation status and matched controls." (PMID 29694444, 2018). "We propose that the MLH1 polymorphism is an important risk factor for development of MLH1 methylation but only in certain cellular environments such as sessile serrated adenomas and BRAF mutant colorectal cancers arising from sessile serrated adenomas." (PMID 29304767, 2018). "BRAF inhibitors provide new treatment alternatives for V600E mutant colorectal cancers, with prolonged overall survival." (PMID 29850361, 2018). "In an extended analysis of 1732 QUASAR 2 and Australian colorectal cancers for which KRAS, BRAF, and MSI status were available, KRAS and BRAF mutations were specifically associated with poor prognosis in MSI-negative cancers." (PMID 30042065, 2018). "Colorectal cancer (CRC) is one of the most common cancers worldwide, with 8–10% of these tumours presenting a BRAF (V600E) mutation." (PMID 30087414, 2018). "BRAF mutant microsatellite stable colorectal cancers with the AA genotype most likely arise in TSAs since the A allele does not predispose to methylation in this context." (PMID 29304767, 2018). "For the dataset of all mutations, the cancer type-specific six gene mutation biomarkers were APC for colorectal cancer, PTEN for endometrial cancer, BRAF for thyroid cancer and MUC16, DNAH5, TTN for cutaneous melanoma." (PMID 30662873, 2018). "Other studies recently showed that vitamin C selectively killed KRAS and BRAF mutant colorectal cancer cells by targeting glyceraldehyde-3-phosphate dehydrogenase (GAPDH)." (PMID 30005692, 2018). "BRAF mutant/MSS cancers form a distinct colorectal cancer entity that shares clinical and molecular features with both BRAF mutant/MSI serrated pathway cancers and the BRAF wild-type cancers of the conventional pathway." (PMID 30598662, 2018). "More recently, primary tumor location, RAS and BRAF status were established as important prognostic factors for colorectal cancer patients." (PMID 29535805, 2018). "The a allele at MLH1–93 is associated with dose dependent increase in MLH1 methylation in dysplastic sessile serrated adenomas and BRAF mutant colorectal cancers." (PMID 29304767, 2018). "These tumors usually have a better prognosis than BRAF-mutated colorectal cancers, but a poorer prognosis than MSI-high colorectal cancers." (PMID 29652830, 2018). "In colorectal cancer, ESP subtypes were correlated with KRAS and BRAF mutation status and also separated primary colon from primary rectal tumors." (PMID 30297789, 2018).
colorectal cancer (continued). "Mutations in KRAS exon 2, BRAF and PIK3CA are commonly present in colorectal cancer (CRC) worldwide, but few data about RAS mutations outside KRAS exon 2 are available for Chinese CRCs." (PMID 29666387, 2018). "Here, we assessed the efficacy of EGFR mAbs in simultaneous and sequential combinations with oxaliplatin in a panel of colorectal cancer cell lines with different genetic backgrounds (wild-type or mutant for KRAS or BRAF)." (PMID 30410004, 2018). "CK7 is minimally present in colorectal cancer but was significantly more frequently upregulated in BRAF mutant/MSS cancers compared to the other cancer subtypes." (PMID 30598662, 2018). "Recent studies have found that they have clinical and molecular features of both the BRAF mutant/MSI and the conventional BRAF wild-type cancers and comprise a distinct colorectal cancer subgroup." (PMID 30598662, 2018). "For colorectal cancer, the mutation status of KRAS and BRAF in is critical for directing choice of therapy." (PMID 29423054, 2018). "Gene mutations in BRAF, MSI-high status, and N-ras differ according to gender among patients with colorectal cancer." (PMID 29976257, 2018). "A connection between this phenomenon and the upregulation of GLUT1 in KRAS and BRAF mutant cells was recently proposed to account for the anti-tumor activity of ascorbate in colorectal cancer." (PMID 30018566, 2018). "The BRAF oncogene is an integral component of the MAP kinase pathway, and an activating V600E mutation occurs in 15% of sporadic colorectal cancer." (PMID 30598662, 2018). "The various pathways of colorectal cancer development result in tumor subtypes that can be classified according to combinations of the main molecular abnormalities, including MSI, CIMP, CIN, BRAF mutations and KRAS mutations." (PMID 29652830, 2018). "It is of note, however, that the in vivo xenograft experiment was carried out with a colorectal cancer line, HT-29, that is wild-type for KRAS and NRAS, but harbors the activating V600E mutation in the BRAF gene." (PMID 30410004, 2018). "To conclude, BRAF inhibitors alone or in combination with other drugs provide a chance for curing BRAF V600E mutant colorectal cancer patients." (PMID 29850361, 2018). "We applied this DTBP platform to compare analyzed plasma with analyzed tumor tissue performed by KRAS and BRAF testing in 14 prospective colorectal cancer (CRC) patients (stages I–IV) and in 10 healthy controls." (PMID 30356899, 2018). "We postulate that BRAF mutant MSS colorectal cancers with the AA-genotype arise in traditional serrated adenomas." (PMID 29304767, 2018). "BRAF mutant MSI colorectal cancers have an excellent 5 year survival of 84.6%, while microsatellite stable BRAF mutant colorectal cancers have a significantly reduced 5-year survival of 40.5%." (PMID 29304767, 2018). "TRAP1 targeting by the mitochondria-directed HSP90 inhibitor Gamitrinib induced apoptosis and inhibited colony formation in BRAF-driven colorectal carcinoma cells, which are known to be poorly responsive to anticancer therapies." (PMID 29621137, 2018). "We target common point mutations in the BRAF, KRAS and PIK3CA oncogenes in archival colorectal cancer samples to precisely map the spatial and morphological context of mutant subclones." (PMID 29222441, 2017). "Upon further evaluation, she was found to have colorectal cancer positive for KRAS and BRAF mutations." (PMID 28811946, 2017). "Furthermore, activating mutations in KRAS or BRAF occur in approximately 50%–60% of patients with colorectal cancer; these mutations are mutually exclusive and are associated with resistance or decreased response to anti-epidermal growth factor receptor therapy in colorectal cancer." (PMID 28152546, 2017). "First, using genome-wide miRNA expression analysis for a set of patients with colorectal cancer followed by the validation analysis for another set of patients, we identified miR-193a-3p as a down-regulated miRNA in BRAF-mutant colorectal cancer." (PMID 29115941, 2017).